MMP1 (matrix metallopeptidase 1)
Diseases named in the same sentence as MMP1 in open-access papers (continued):
Sharing a sentence is not in itself a finding about the gene and the disease.
breast carcinoma (continued). "Significantly higher values of RANKL, CTKS, PTH1R, IL-6, IL-1β and MMP-1 were found in bone fragments cultured with MCF-7 breast cancer cells in comparison to bone fragments cultured without cancer cells, both in normoxic and hypoxic conditions." (PMID 27765913, 2016). "It is possible that the Jun/AP1 complexes formed in the cellular context of metastatic breast cancer cells can interact with the AP1 sequence of the MMP1 promoter, but not with that of c-Jun." (PMID 27494896, 2016). "On the transcriptional basis, we observed reduced mRNA expression of MMP1, -3 and -9 after LASP1 knockdown in MDA-MB-231 breast cancer cells that could be confirmed on protein level." (PMID 27588391, 2016). "In addition, it also remained conflicting as to the influence of MMP-1, MMP-2, MMP-11, MMP-13 and MMP-14 expression on the survival of breast cancer patients." (PMID 26270045, 2015). "Instead of MMP1, MMP11 is over-expressed in MCF-7 spheroids and in a variety of human carcinomas, and MMP11 expression directly correlates with improved cell-matrix adhesion, tumour development and poor prognosis of breast cancer patients." (PMID 26513020, 2015). "However, 15d-PGJ2 increased the expression of matrix metalloproteinase (MMP)-1 and vascular endothelial growth factor to induce angiogenesis in MCF-7 breast cancer cells." (PMID 25859665, 2015). "Besides, it had been demonstrated that Fra-1 directly induced MMP-1 and MMP-9 promoter activities in breast cancer cells and stimulated MMP-2 and MMP-9 expression to enhance the motility and invasion of lung cancer cells." (PMID 26337460, 2015). "In this translational study, we hypothesized, that MMP1 is involved in CTC release and CTCs are detected more often in breast cancer patients with high MMP1 expression in primary tumor or tumor associated stroma." (PMID 24972610, 2014). "In this study, we analyzed the differences in the immunoreactivity of MMPs (MMP-1, 2, 7, 9, 11, 13, and 14) and TIMPs (TIMP-1, 2, and 3) in breast carcinoma representing three subtypes, luminal A, HER2-overexpressing, and basal-like, based on immunohistochemical findings." (PMID 25510449, 2014). "This experimental finding could be in line with previous clinical data indicating that MMP-1 and MMP-13 seem to be related with different metastatic profiles in breast cancer." (PMID 25527274, 2014). "After 7 h of artesunate treatment, the effect switched and supernatants of treated cells had elevated MMP-1 concentrations in comparison to non-treated breast cancer cells." (PMID 21637790, 2011). "In our study MMP-1 overexpression in tumour cells did not have any significant differences within breast cancer subtypes." (PMID 21835023, 2011). "Stromal-derived MMP1 was recently shown to cleave and activate the G-protein-coupled receptor, protease-activated receptor one (PAR1), leading to activation of intracellular signal that regulates the invasion process in breast cancer cells." (PMID 19489099, 2009). "Furthermore, MMP-1 and MMP-2 have been described as genes that selectively mediate lung metastasis in the MDA-MB-231 xenograft model of breast cancer and are members of a lung metastasis gene signature for human breast cancers." (PMID 19243594, 2009). "The tissue levels of at least MMP-1, MMP-2, MMP-9, MMP-11, membrane type (MT) 1-MMP, tissue inhibitors of metalloproteinases (TIMP) 1 and TIMP-2 have been correlated with poor outcome of breast cancer patients." (PMID 19243594, 2009). "Expression of MMP-1 mRNA was higher in breast cancer tissue grade 2 than in normal breast tissue (p = 0,0027)." (PMID 19531263, 2009). "All other estrogen receptor (ER)-α-negative but not ER-α-positive breast cancer cell lines expressed lower but detectable levels of MMP-1." (PMID 17062128, 2006).
breast carcinoma (continued). "Under these conditions, four secreted MMPs were identified: MMP-1, MMP-3, MMP-9, and MMP-13 and the membrane-anchored MMP, MT1-MMP in all 3 breast cancer cell lines (MDA-231 cells shown, results similar in all 3 breast cancer cell lines)." (PMID 15701164, 2005). "Also, in vitro MMP-1 expression was up-regulated by cell–cell contact between BMS and breast carcinoma cells." (PMID 11953862, 2002). "Additionally, MMP1 upregulation was reported to enhance multi-drug resistance to MCF-7 breast cancer cells, as evidenced by the increase of the IC50 values of ADR, vincristine, and paclitaxel in MCF-7 breast cancer cells overexpressing MMP1." (PMID 40214422, 2025). "Notably, this phenomenon may be attributed to the activation of MMP-1, which is observed to be upregulated by PRDX3 in the breast cancer cells." (PMID 38321552, 2024). "For breast cancer, YBX1 has been regarded as potential biomarker with poor outcome and silencing YBX1 could inhibit invasive potential through binding its downstream target, such as CORO1C and MMP1." (PMID 34991621, 2022). "In our results, high expression of MMP1, CD24, SDC1, and SPP1 correlated to the development of breast cancer, worse OS and immune cell infiltration, indicating that MMP1, CD24, SDC1, and SPP1 might be as the potential prognostic biomarkers and immunotherapy targets for breast tumor." (PMID 35037689, 2022). "Hence, further study is required to determine whether MMP1, CD24, SDC1, and SPP1 could be used as biomarkers or immune therapy targets in breast cancer." (PMID 35037689, 2022). "Apelin stimulates MCF-7 BC cell proliferation via the dose-dependent induction of cyclin D1 and amplified in breast cancer 1 (AIB1) and invasion potential by upregulating MMP1 expression, a mechanism also described in A549 lung adenocarcinoma cells." (PMID 33670492, 2021). "Breast cancer cell is known to produce numerous osteolytic factors including parathyroid hormone-related protein (PTHrP), IL-1, IL-6, IL-8, IL-11, vascular endothelial growth factor (VEGF), connective tissue growth factor (CTGF), matrix metallopeptidase 1 (MMP1), hepatocyte growth factor, etc12–16." (PMID 31040267, 2019). "In addition, how dysregulated MMP1 is related to the EMT of MDR breast cancer cells have not been fully revealed." (PMID 28334049, 2017). "Second, high MMP1 mRNA expression correlated with worse overall survival among grade II (HR = 1.75; p = 0.011), nodal-negative (HR = 2.00; p = 0.00028), ER-positive (HR = 1.61; p = 0.00027) and HER2-negative (HR = 3.17; p = 0.029) patients with breast cancer by using Kaplan-Meier plotter database." (PMID 29207651, 2017). "Moreover, R-cad was found to inhibit expression of MMP-1, MMP-2, and Cox-2 in mammary tumors." (PMID 27783992, 2016). "The basal levels of MMP-1 and MMP-9 are increased in various breast cancer cells, including MCF7, in response to heregulin-β1 via activation of MAPK/ERK pathway and overexpression of Ets1 in ErbB2 expressing breast cancer cells increases the expression of MMP-1." (PMID 24709902, 2014). "To assess if MMP-1 could have a major role in breast cancer-induced osteolytic lesions, we analyzed the effect of MMP-1 knockdown in bone osteolysis in a mouse model of breast cancer bone metastases." (PMID 23696795, 2013). "We evaluated genetic variation in MMP1 (9 SNPs), MMP2 (8 SNPs), MMP3 (4 SNPs), and MMP9 (3 SNPs) and breast cancer risk among Hispanic (2111 cases, 2597 controls) and non-Hispanic white (NHW) (1481 cases, 1586 controls) women in the Breast Cancer Health Disparities Study." (PMID 23696797, 2013). "In this study, we show that the targeted knockdown of MMP-1 in 231-BR and 231-BR3 cells not only reduced primary tumor growth, but also significantly inhibited the invasiveness of these two brain-seeking metastatic breast cancer cells and attenuated formation of experimental brain metastases." (PMID 23217186, 2012).
breast carcinoma (continued). "However, MMP-1 mRNA is shown to be up-regulated in basal-type breast cancers when compared with non-basal-type breast cancers." (PMID 21835023, 2011). "In addition to MMP-2 and MMP-9, MMP-1 has also been used as an accurate marker in a three markers scores model, including MMP-1, hepatocyte growth factor, and chemokine ligand 5, to predict axillary lymph node metastasis (LNM) positivity in breast cancer patients." (PMID 37181043, 2023). "Although no MMP-1a, the mouse ortholog of human MMP1, was detected in the secretome of PyMT cells, other molecular pathways can be activated by the extracellular form of the 14-3-3β protein, promoting the progression of mammary cancer in the PyMT breast cancer model." (PMID 29088746, 2017). "However, the functional role of MMP1 in MDR of breast cancer cells is not well characterized." (PMID 28334049, 2017). "This retrospective cohort study shows the immunohistochemical expression levels of MMP-1, MMP-2, MMP-3, and MMP-9 in 154 women with breast cancer and 42 women without tumor disease." (PMID 34445715, 2021). "To test this, firstly we investigated the influence of breast cancer cells on MMP1 and MMP11 gene expression by performing PBMC-breast cancer cells co-cultures (not selected on the basis of MMP11 expression)." (PMID 33396463, 2020). "Here we report that in non-metastatic, estrogen receptor-positive breast cancer (ER+ BC) cells, induced MLK3 expression robustly upregulates the oncogenic transcription factor, FOS-related antigen-1 (FRA-1), which is accompanied by elevation of matrix metalloproteinases (MMPs), MMP-1 and MMP-9." (PMID 28604765, 2017). "In this study we evaluated genetic variation in MMP1, MMP2, MMP3, and MMP9 using data from a large collaborative case-control study of breast cancer in Hispanic and non-Hispanic white women (NHW) from the United States and Mexico." (PMID 23696797, 2013). "Plasma MMP1 and MMP8 levels did not correlate among controls (rs = 0.10, p = 0.54, data not shown) nor among breast cancer patients (rs = 0.009, p = 0.90, data not shown)." (PMID 18366705, 2008). "While one study showed the prognostic significance of fibroblastic MMP-1 expression, another study reported that stromal MMP-1 expression is not significant and that high MMP-1 expression in tumor cells is an independent negative prognostic factor for breast cancer-specific survival." (PMID 36741729, 2022). "In conclusion, it is unclear whether HIIT influences levels of MMP in breast cancer patients undergoing anthracycline-based chemotherapy yet MMP-2 was significantly increased both the HIIT and CON group; with no changes on MMP-1, -7, -10, TIMP-1 and -2." (PMID 32246106, 2020). "However, MMP1 gene expression in PBMC from breast cancer patients was significantly increased only after co-cultures with CAF or normal fibroblasts, but not after co-culture with breast cancer cell lines." (PMID 33396463, 2020). "In contrast to nontreated con cells, for senescent human breast cancer MDA-MB-231 cells, the factors detected by arrays and secreted at a significant level are FGF-6, GM-CSF, IGFBP-1, MCP-1, IL-6, IL-1α, GRO a/b/g, GRO α, IL-8, MIP, MIP-1α, uPAR, ICAM-1, and MMP-1." (PMID 30871042, 2019).
melanoma (103 papers, 1999 to 2025). A malignant, usually aggressive tumor composed of atypical, neoplastic melanocytes. "Clinical research has indicated that MMP-1 is overexpressed in numerous malignancies, and its presence is associated with a poor prognosis, particularly in melanoma patients." (PMID 39769318, 2024). "Galectin-3 has previously been reported to increase secretion of MMP-1 and −9 in melanoma cells by binding to lysosome-associated membrane protein-1 (LAMP1)." (PMID 37055381, 2023). "MMP-1 is upregulated in melanoma in vivo and both MMP-1 and -3 are associated with shorter disease-free survival." (PMID 36005056, 2022). "A 1G/2G deletion/insertion polymorphism at position -1607 in the MMP-1 promoter has been associated with differential expression of this gene in fibroblast and melanoma cells, with the 2G genotype associated with higher basal levels of MMP1 mRNA." (PMID 21244711, 2011). "The rs1799750 MMP1 1G/2G promoter polymorphism has been shown to influence MMP1 transcription in both normal fibroblasts and in melanoma cells." (PMID 19551141, 2009). "Loss of heterozygosity (LOH) has been described at the MMP-1 -1607/2G polymorphic site in malignant melanoma." (PMID 17311017, 2007). "MMP1 has also been linked to tumorigenesis and metastasis of melanoma by generating activated TGFβ." (PMID 40574005, 2025). "The prototypical MMP1, collagenase 1, has been implicated in melanoma and premature skin aging." (PMID 33809637, 2021). "Indeed, high levels of MMP-1 expression in melanoma cells have been seen in cells homozygous for the 1G allele, which are mediated through both ERK1/2 and p38 mitogen-activated protein kinase pathways, while only the ERK pathway targets the 2G allele." (PMID 23776649, 2013). "Down-regulation of E-cadherin and high levels of MMP1 and integrin αVβ3 are associated with transition from the radial non-invasive to the invasive vertical growth phase and the acquisition of metastatic potential in melanoma." (PMID 20969766, 2010). "Also MMP-1 expression is highly associated with melanoma progression." (PMID 20631829, 2010). "The overexpression of MMP-1 in melanoma cells is driven by constitutive activation of the ERK pathway, attributed to BRAF mutation and autocrine fibroblast growth factor signaling." (PMID 40574005, 2025). "Except for the melanoma tissue of DIM that revealed intense co-staining for MMP1 and S100, the staining of the other tumor sections for S100 was less pronounced, or absent (ELL meta, i.e., ELL liver metastasis)." (PMID 38891088, 2024). "Several studies have shown that melanoma cells can express a specific pool of MMPs (MMP-1, MMP-2, MMP-9, MMP-13, and MT1-MMP) as well as their tissue inhibitors (TIMP-1, TIMP-2, and TIMP-3)." (PMID 39594665, 2024). "The highest difference in mean transcription levels was exhibited by MMP1 with a 125-fold upregulation in gray horse melanoma compared to intact skin." (PMID 38891088, 2024). "In the next step, we established equine primary melanoma cells from fresh tumor material and comparatively assessed the expression of MMP1 in tumor tissue and primary cells derived therefrom by immunofluorescence staining (IF)." (PMID 38891088, 2024). "The thereby determined 125-fold upregulation of MMP1 in melanoma tissue was subsequently validated by RT-qPCR from further ex vivo samples." (PMID 38891088, 2024). "In other studies, increased MMP-1 activity was shown to be correlated with increased invasiveness and metastasis in melanoma." (PMID 39769318, 2024). "Overall, the presented data point to MP expression being deregulated in gray horse melanoma, and suggest that MMP1 has an active role in gray horse melanoma by driving EMT-mediated tumor cell dissemination via the degradation of the extracellular matrix." (PMID 38891088, 2024).
melanoma (continued). "Herein, we report on the differential transcription of MPs in gray horse melanoma compared to intact skin tissue, and on the expression of MMP1 in gray horse melanoma tissue and primary cells established therefrom." (PMID 38891088, 2024). "RNAseq revealed the deregulation of several MPs in gray horse melanoma and, notably, a 125-fold upregulation of matrix metalloproteinase 1 (MMP1) that was further confirmed by RT-qPCR from additional tumor material." (PMID 38891088, 2024). "The IF staining of melanoma tissue versus intact skin for MMP1 and tumor marker S100 revealed MMP1 expression in all lesions." (PMID 38891088, 2024). "Overall, we show that the MT expression signatures of gray horse and human cutaneous melanoma differ significantly, with MMP1 being overexpressed in tumor tissue and primary melanoma cells on the mRNA and protein level." (PMID 38891088, 2024). "For example, a study analyzing the expression of MMPs in melanoma found that MMP-1, MMP-2, MMP-3, MMP-7, MMP-9, and MMP-13 showed increased levels in melanoma tissues compared to normal tissues." (PMID 39200315, 2024). "In the same experiment, we also assessed melanoma cells derived from DOL for relative MMP1 transcription in comparison to the intact skin from this horse." (PMID 38891088, 2024). "It has also been proved that MMP-1 increased expression in invasive melanoma when compared to in situ melanomas." (PMID 39769318, 2024). "At the same time, the low concentration of GSO-ILE reduced the amount of melanin in melanoma cells and the production of MMP-1 by fibroblasts and increased the content of human type I collagen." (PMID 39458914, 2024). "Matrix metalloproteinase-1 (MMP-1) serves as an extracellular matrix degrading enzyme that facilitates tumor migration and invasion, promoting melanoma growth and metastasis." (PMID 38812776, 2024). "MMP-1, -2, -3, -9, -13, and -14 have been shown to play an important role in the development of melanoma." (PMID 39769318, 2024). "The MMP1 staining of melanoma sections of GYN and BON were difficult to interpret because of tissue denaturation, as reflected by unspecific DAPI staining (blue signal)." (PMID 38891088, 2024). "The relative quantification of MMP1 transcription in melanoma versus intact skin was carried out by the comparative ΔCT method." (PMID 38891088, 2024). "The knockdown of MMP-1 in melanoma mouse cell lines was reported to decrease the tumor’s capacity to metastasize." (PMID 39063046, 2024). "In the normal skin obtained from melanoma-affected horses (top row), MMP1 expression (green signal) was exhibited by glandular cells (yellow arrows)." (PMID 38891088, 2024). "The RNA-seq approach revealed a deregulated MP transcription pattern in gray horse melanoma, with MMP1 showing the most significant upregulation in tumor tissue compared to intact skin." (PMID 38891088, 2024). "In aggregate, our present study also suggested the pro-angiogenetic roles of TAMs through IL-23p19, CXCL5 and MMP-1 in melanoma." (PMID 36980564, 2023). "Interfering Twist1 inhibited epithelial-mesenchymal transition (EMT) and limited lipopolysaccharide-induced inflammation, migration, and invasion in A2058 melanoma cells with the decrease of MMP1/9, VEGF, TNF-α, and IL-6." (PMID 35321317, 2022). "MMP-1 activation is correlated with promoting melanoma progression into the more aggressive ventricle growth phase." (PMID 36005056, 2022). "MMP-1, a collagenase, is produced by melanoma cells and peritumoral fibroblasts, increasing tumor growth and metastasis." (PMID 35558554, 2022). "Several matrix metalloproteinases are expressed in melanoma, the tumor, and the peritumoral stroma, including MMP-1, MMP-2, MMP-9, MMP-13, and MMP-14." (PMID 35558554, 2022). "For example, ADAM9 promotes the invasion and metastasis of cancer cells in melanoma by activating MMP1 and MMP2, while ADAM17 can activate MMP2 to treat the disease (prostate cancer and lung injury) by promoting angiogenesis." (PMID 36172139, 2022).